HDDC3 (HD domain containing 3)
Description:
ppGpp hydrolyzing enzyme involved in starvation response.
Synonyms: MESH1; (ppGpp)ase; MGC45386; MYNRL15
Tractability: Small molecule: a structure with a bound ligand is known; it has a high-quality binding pocket. PROTAC: ubiquitination databases record sites on it; its protein half-life has been measured.
Gene: Protein-coding gene on chromosome 15 (90,929,968 to 90,935,196, reverse strand). Ensembl gene ENSG00000184508.
Subcellular location (Human Protein Atlas): Cytosol; Nucleoplasm
Gene Ontology:
Molecular function: protein binding; guanosine-3',5'-bis(diphosphate) 3'-diphosphatase activity
Genetic constraint (gnomAD): Loss-of-function variants: 17 observed, 17.13 expected, observed/expected ratio (o/e) 0.99, 90% interval 0.68 to 1.49. The upper end of that interval is the gene's LOEUF score, 1.49, which puts it in group 6 of 6, group 1 being the genes least tolerant of losing a copy. Missense variants: 247 observed, 217.48 expected, observed/expected ratio (o/e) 1.14, 90% interval 1.02 to 1.26. Synonymous variants: 107 observed, 93.67 expected, observed/expected ratio (o/e) 1.14, 90% interval 0.98 to 1.34.
Homologues: Orthologues: chimpanzee HDDC3 (99% identical), macaque HDDC3 (99% identical), mouse Hddc3 (96% identical), rabbit HDDC3 (94% identical), dog HDDC3 (94% identical), guinea pig HDDC3 (94% identical), pig HDDC3 (80% identical), rat Hddc3 (78% identical), tropical clawed frog hddc3 (75% identical), zebrafish hddc3 (74% identical), Drosophila melanogaster Mesh1 (58% identical), Caenorhabditis elegans ZK909.3 (53% identical).
Diseases named in the same sentence as HDDC3 in open-access papers:
HDDC3 is named in the same sentence as 16 diseases in open-access papers, as found by Europe PMC text mining. Sharing a sentence is not in itself a finding about the gene and the disease. The quoted sentences say what the papers report.
breast tumors (1 paper, 2014). "The HDDC3 gene is expressed at higher levels by several different tumor types, including breast tumors, than by normal tissue." (PMID 25390939, 2014).
diabetes (1 paper, 2024). "For instance, Hddc3 and Zfp69, whose expression is downregulated under light conditions, are involved in ferroptosis and insulin sensitivity during diabetes, respectively." (PMID 38252153, 2024).
cancer (7 papers, 2014 to 2024). A tumor composed of atypical neoplastic, often pleomorphic cells that invade other tissues. "There is very little reported evidence on the involvement of HDDC3 or the hsa-miR-1224-3p in cancer, indicating a novel association with risk." (PMID 25390939, 2014).
tumor (4 papers, 2014 to 2023). "Based on the antitumor phenotypes associated with MESH1 knockdown, we analyzed the prognostic significance of MESH1 (HDDC3) expression in the tumor datasets." (PMID 35273140, 2022).
metabolic disease (1 paper, 2022). A congenital disorder (due to inherited enzyme abnormality) or acquired (due to failure of a metabolically important organ) disorder resulting from an abnormal metabolic process. "HDDC3 is a cytosolic NADPH phosphatase that regulates ferroptosis, and ferroptosis is reportedly involved in endocrine and metabolic diseases, including PCOS." (PMID 35794640, 2022).
HDDC3 also shares sentences with these, for which no sentence is quoted: breast carcinoma (2 papers); chondrosarcoma (1); colon cancer (1); fibrosarcoma (1); follicular lymphoma (1); gastric cancer (1); lung carcinoma (1); meningioma (1); neuroblastoma (1); non-small cell lung carcinoma (1); renal cell carcinoma (1).